HOTTIP (HOXA distal transcript antisense RNA)
Diseases named in the same sentence as HOTTIP in open-access papers (continued):
Sharing a sentence is not in itself a finding about the gene and the disease.
colorectal cancer (14 papers, 2016 to 2025). A primary or metastatic malignant neoplasm that affects the colon or rectum. "From a clinical perspective, elevated levels of HOTTIP were detected in colorectal cancer tissues and were strongly associated with an unfavorable prognosis in patients with colorectal cancer." (PMID 40624028, 2025). "In contrast, in colorectal cancer lower EV HOTTIP levels were associated with decreased OS, but in the same line they observed that low tumor levels were also related to worse postsurgical prognosis of these patients." (PMID 34111710, 2021). "Studies have also reported HOTTIP as a diagnostic or prognostic biomarker in gastric and colorectal cancers; however, to date, only one study has reported the discriminatory role of circulating HOTTIP in liver diseases." (PMID 34185961, 2021). "Our data presented herein suggest that HOTTIP may be a diagnostic and prognostic biomarker for colorectal cancer." (PMID 40624028, 2025). "We further performed a set of experiments to elucidate the molecular mechanisms by which HOTTIP promotes the proliferation and malignant progression of colorectal cancer." (PMID 40624028, 2025). "From a clinical perspective, high levels of HOTTIP are strongly correlated with poor prognosis in patients with colorectal cancer." (PMID 40624028, 2025). "Together, these results suggest that HOTTIP depletion significantly attenuates Hh/GLI signaling activation-mediated proliferation of colorectal cancer cells." (PMID 40624028, 2025). "In colorectal cancer, HOTTIP is highly expressed, promoting cell proliferation, migration, and invasion, while knockdown of HOTTIP inhibits these processes and induces apoptosis by targeting SGK1." (PMID 40624028, 2025). "From a biological perspective, high expression of HOTTIP can promote colorectal cancer cell proliferation and survival as well as tumorigenesis." (PMID 40624028, 2025). "From a clinical perspective, high levels of the lncRNA HOTTIP were detected in colorectal cancer tissues and were strongly correlated with poor prognosis in colorectal cancer patients." (PMID 40624028, 2025). "We assessed the viability of the colorectal cancer organoids via an ATP assay and found a dramatic increase in the viability of the HOTTIP-overexpressing colorectal cancer organoids." (PMID 40624028, 2025). "We subsequently evaluated the expression of HOTTIP in 120 colorectal cancer samples and 11 randomly matched adjacent normal tissues." (PMID 40624028, 2025). "It has been described that knockdown of HOTTIP, ranked eighth, inhibits the proliferation and migration of colorectal cancer cells." (PMID 38431702, 2024). "HOTTIP provides another example of lncRNA upregulated in several types of cancer, such as hepatocellular carcinoma, gastric cancer, colorectal cancer, pancreatic cancer, lung cancer, prostate cancer, and osteosarcoma." (PMID 35054945, 2022). "Previous studies showed that in colorectal cancer cells, HOTTIP knockdown also inhibited migratory capability and significantly decreased lung metastatic lesions in mouse xenograft mode, similar to the results in our study." (PMID 27806322, 2016). "Furthermore, we analyzed the correlations between the expression of HOTTIP and the pathological features of colorectal cancer tissues." (PMID 40624028, 2025). "Because we found that Hh signaling activates HOTTIP, which in turn induces colorectal cancer cell proliferation, we hypothesize that HOTTIP may also promote colorectal cancer progression." (PMID 40624028, 2025).
colorectal cancer (continued). "Moreover, lncRNA HOTTIP overexpression increased the proliferation and viability of organoids derived from colorectal cancer patients." (PMID 40624028, 2025). "Finally, analysis of a colorectal cancer single-cell dataset (GSE132465) revealed high HOTTIP expression in the epithelial cells of tumor tissues, further supporting its role in cancer progression." (PMID 40624028, 2025). "The viability of colorectal cancer organoids with HOTTIP overexpression was dramatically increased." (PMID 40624028, 2025). "Collectively, these results underscore the important role of HOTTIP in colorectal cancer progression and suggest that HOTTIP may serve as an independent prognostic biomarker." (PMID 40624028, 2025). "Upregulation of HOTTIP promotes cancer growth and invasion in colorectal cancer." (PMID 34983537, 2022). "Additionally, the detection of HOTTIP in the exosome samples of patients has been recognized as a possible prognosis marker in colorectal cancer." (PMID 35054945, 2022). "Furthermore, studies in colorectal cancer cells show that HOTTIP regulates metastasis partly through the down-regulation of the tumor suppressor DKK1." (PMID 33081056, 2020). "Compared with the human embryonic intestinal mucosa-derived cell line CCC-HIE-2, all five tested colorectal cancer cell lines (SW480, HCT116, SW620, HT-29, and DLD-1) presented increased expression of HOTTIP." (PMID 40624028, 2025). "To determine the biological function of HOTTIP in vivo, we established colorectal cancer xenograft models in mice using HCT116 cells with HOTTIP overexpression and HT-29 cells with HOTTIP knockout." (PMID 40624028, 2025). "Next, we investigated the effects of HOTTIP knockout and knockdown on Hh/GLI signaling-dependent colorectal cancer cell proliferation." (PMID 40624028, 2025). "To validate these results, we used a colorectal cancer tissue array and performed RNA FISH, confirming elevated HOTTIP levels in cancerous tissues compared with adjacent normal tissues." (PMID 40624028, 2025). "Further, a recent study reveals that the knockdown of the long non-coding RNA HOTTIP inhibits cell proliferation, migration, and significantly suppresses the expression of glycogen synthase kinase 3β, β-Catenin and MYC in colorectal cancer." (PMID 33081056, 2020). "Additionally, we examined the correlation between HOTTIP and GLI2 expression and the pathological features of colorectal cancer tissues." (PMID 40624028, 2025). "While these findings highlight HOTTIP as an important player in colorectal cancer pathogenesis, the detailed molecular mechanisms through which HOTTIP contributes to colorectal cancer progression are still not fully understood." (PMID 40624028, 2025).
lung carcinoma (13 papers, 2016 to 2025). "As for lung cancer, one study on Chinese patients figured out that C allele of HOTTIP rs5883064 or A allele of HOTTIP rs1859168 increased lung cancer risk." (PMID 40616679, 2025). "Previous studies have linked HOTTIP to the development of lung cancer and inflammatory associated diseases." (PMID 38545254, 2024). "Gong et al13 found that SNPs in HOTTIP, H19, and CCAT2 were associated with lung cancer risk, and SNPs in MALAT1, H19, CCAT2, HOTAIR, and ANRIL were related to lung cancer patients’ response to platinum‐based chemotherapy." (PMID 30980423, 2019). "Interestingly, EMT promotion is a recurring role of HOTTIP, enabling cancer cells to become more invasive and metastatic, as observed in breast, pancreatic, and lung cancers." (PMID 40616679, 2025). "LncRNA HOTTIP mediates the ceRNA network, which interferes with the expression of anti-apoptotic factor BCL-2, suggesting that HOTTIP may serve as a valuable biomarker in lung cancer patients." (PMID 33628581, 2021). "Furthermore, HOTTIP was reported to inhibit cell apoptosis and promote the progression of prostate cancer and lung cancer." (PMID 28938659, 2017). "In addition, many studies have shown that HOTTIP could function as a ceRNA to promote the expression of oncogenic genes in renal cell carcinoma, lung cancer, and prostate cancer." (PMID 31032351, 2019). "Moreover, HOTTIP was upregulated in lung cancer tissues and promoted the tumor progression, suggesting that HOTTIP is crucial in maintaining lung homeostasis and that its dysregulation may contribute to the development of lung disease even lung cancer." (PMID 38545254, 2024).
prostate carcinoma (12 papers, 2017 to 2023). A carcinoma that arises from epithelial cells of the prostate gland. "The HOXA transcript at the distal tip (HOTTIP) lncRNA plays an important role in carcinogenesis, however, the underlying role of HOTTIP in prostate cancer (PCa) remains unknown." (PMID 29884766, 2018). "In prostate cancer, HOTTIP forms a complex with the transcription factor TWIST1 and with WDR5 and produces upregulation of HOXA9 levels through chromatin regulation which correlates with an aggressive cellular phenotype." (PMID 30819158, 2019). "Interestingly, HOTTIP also sustains prostate cancer cisplatin resistance through decreasing the apoptosis of PCa cells." (PMID 34103477, 2021). "Lnc-HOTTIP is evidently highly expressed in prostate cancer samples compared to controls." (PMID 34103477, 2021). "Interestingly, another study has also proved that knockdown of HOTTIP exerts an inhibitory function on prostate cancer cell proliferation and an accelerative effect on the sensitivity to cisplatin." (PMID 33585440, 2020). "The clustered miR-216 family has recently been reported to play a tumor-suppressive role in human cancer and HOTTIP could competitively sequester miR-216a in small cell lung cancer and prostate cancer." (PMID 32457911, 2020). "Moreover, HOTTIP modulates cancer stem cell properties by binding WDR5 and activating HOXA9, which enhances the Wnt/β-catenin pathway in prostate cancer stem cells." (PMID 30819158, 2019). "The main role of HOTTIP and HOXA13 in prostate cancer has been underlined by the recent finding that PC risk elements are mainly related to HOXA13 and HOTTIP expressions, but not to other HOXA locus genes." (PMID 31137568, 2019).
liver cancer (11 papers, 2015 to 2025). An epithelial or non-epithelial malignant neoplasm that arises from the liver. "According to literature survey, many DE lncRNAs, such as MALAT1, CDKN2B-AS1, and HOTTIP, have been reported to be associated with liver cancers." (PMID 32760422, 2020). "In liver cancer cell lines and tumors, HOTTIP is closely associated with expression of HOXA13 and knockdown of HOTTIP decreases expression of HOXA13." (PMID 25912306, 2015). "Our data are consistent with a pioneering study demonstrating that decreased expression of HOXA13 led to a clear reduction of HOTTIP expression in liver cancer-derived cell lines." (PMID 25889214, 2015). "Previous studies in foreskin fibroblasts show that HOTTIP knockdown decreases expression of 5′ HOXA genes, particularly HOXA13 and in liver cancer cells and tumors, there was a parallel expression of HOTTIP and HOXA13 and siHOTTIP decreased HOXA13 mRNA levels." (PMID 25912306, 2015). "Notably, HOXA13 and HOTTIP were found to be highly expressed in the same neoplastic hepatocyte populations and in liver cancer cell lines." (PMID 39329491, 2024). "Recently, it was reported that HOTTIP is a negative prognostic factor in patients with liver cancer, and increased HOTTIP expression was associated with enhanced liver cancer metastasis." (PMID 25889214, 2015). "Some lncRNA, which where found to be significantly increased in other liver cancers, such as HULC (highly upregulated in liver cancer), HOTAIR and HOTTIP only showed a mild increase in FLC; while others, such as H19, showed a decrease." (PMID 29535801, 2018). "Tsang and colleagues found that downregulation of HOTTIP markedly reduced the expression of numerous HOXA genes and weakened liver cancer growth and metastasis both in vivo and in vitro." (PMID 28938659, 2017). "Unlike liver cancer cells, HOXA13 is not the downstream target of HOTTIP, but other HOX genes, such as HOXA10, HOXB2, HOXA9 and HOXA1 are increased by HOTTIP." (PMID 27429196, 2016).
lymph node metastasis (10 papers, 2015 to 2024). "The association between the HOTTIP level and overall survival (OS), lymph node metastasis (LNM), or clinical stage was subsequently analyzed." (PMID 32566641, 2020). "To further explore the clinical value of HOTTIP in cancer, we collected all relevant studies and investigated the association between HOTTIP level and lymph node metastasis (LNM) or overall survival (OS)." (PMID 27806342, 2017). "Exosomal HOTTIP was reported to be associated with poor overall survival, while exosomal ZFAS1 was associated with lymph node metastasis and poorer clinical stage." (PMID 35465325, 2022). "Univariate analysis of overall survival revealed that T stage (P = 0.038), Lymph node metastasis (P = 0.011), Early recurrence (P = 0.009), HOTTIP-005 expression (P < 0.001) and RP11-567G11.1 expression (P < 0.001) were prognostic indicators." (PMID 26447755, 2015). "Multivariate analysis indicated that Lymph node metastasis (P = 0.009), Early recurrence (P = 0.007), HOTTIP-005 expression (P < 0.001) and RP11-567G11.1 expression (P = 0.003) were independent prognostic indicators for overall survival of patients with PC." (PMID 26447755, 2015). "Moreover, the results of another study identified that HOTTIP is upregulated in TSCC tissues with lymph node metastasis compared to those without lymph node metastasis." (PMID 33520725, 2020).
renal cell carcinoma (9 papers, 2019 to 2025). "However, the expression and function of HOTTIP in renal cell carcinoma (RCC) were rarely reported." (PMID 38968431, 2024). "Moreover, it was proven that HOTTIP directly targets miR-615 (as it acts as a competing endogenous RNA (ceRNA) for miR-615-3p, resulting in the activation of its endogenous targets), affecting the growth of renal cell carcinoma." (PMID 34069089, 2021). "In renal cell carcinoma (RCC), it was reported that the HOTTIP down-regulation attenuated RCC cell proliferation, migration, and invasion, which could be rescued by miR-506 down-regulation." (PMID 40959107, 2025). "NEAT1, THOR, and HOTTIP via targeting IGF2 affect carcinogenic processes in colorectal cancer, tongue squamous cell carcinoma, and renal cell carcinoma." (PMID 33768092, 2021). "The HOTTIP oncogenic functions are mediated through negative regulation by a reciprocal repression of miR-615-3p which in turn regulates IGF-2 expression, with this molecule being a direct target gene of HOTTIP and of miR-615-3p, at least in renal cell carcinoma." (PMID 32605009, 2020).
small cell lung carcinoma (9 papers, 2017 to 2025). Small cell lung cancer (SCLC) is a highly aggressive malignant neoplasm, accounting for 10-15% of lung cancer cases, characterized byrapid growth, and early metastasis. "For instance, lncRNA-KRTAP5-AS1 and lncRNA-TUBB2A regulate CLDN4 and influence tumor formation and metastasis via a ceRNA-mediated regulatory network in GC, while HOTTIP promotes small cell lung cancer via a HOTTIP/miR-574-5p/EZH1-associated ceRNA network." (PMID 30774556, 2019). "HOTTIP was also demonstrated to act as a ceRNA by sponging miR-574-5p, which promotes the progression of small cell lung cancer (SCLC) by affecting the expression of polycomb group protein EZH1." (PMID 39937018, 2025). "HOTTIP functions as an oncogene in small cell lung cancer by sponging miR-574-5p and positively regulating the expression of EZH1." (PMID 40624028, 2025). "HOXA Distal Transcript Antisense RNA (HOTTIP) has been identified as upregulated lncRNA in small cell lung cancer (SCLC) tissues, and to be correlated with shorter survival times for SCLC patients." (PMID 34692550, 2021). "Additionally, lncRNA HOTTIP enhances drug resistance in small cell lung cancer (SCLC) by promoting BCL-2 expression." (PMID 31777598, 2019).
acute myeloid leukemia (8 papers, 2021 to 2026). Acute myeloid leukemia (AML) is a group of neoplasms arising from precursor cells committed to the myeloid cell-line differentiation. "lncRNA HOTTIP is highly expressed in acute myeloid leukemia (AML) to mediate HOXA topologically associated domain (TAD) formation and mediated R-loop formation to drive oncogene transcription." (PMID 38374003, 2024). "In mixed-lineage leukemia (MLL), rearranged (MLLr+), or nucleophosmin 1 (NPM1)-mutated (NPM1c+) acute myeloid leukemia, HOTTIP expression is upregulated, which is associated with a poor survival rate in AML patients." (PMID 36983041, 2023). "For example, current research has established that HOTTIP is an oncogene in acute myeloid leukemia (AML), and it has been demonstrated to be significantly expressed in a variety of malignancies." (PMID 41614928, 2026). "This includes acute myeloid leukemia (AML) where HOTTIP facilitates leukemogenesis through R-loop creation and HOXA9 regulation." (PMID 40616679, 2025). "HOTTIP is frequently reported as an oncogenic lncRNA in several cancers, including acute myeloid leukemia, head and neck squamous cell carcinoma, and HCC." (PMID 35110549, 2022). "For example, it has been shown that the lncRNA HOTTIP is not only overexpressed in acute myeloid leukemia (AML) patients but is key in maintaining stemness via regulation of the HOXA gene." (PMID 35954194, 2022).
non-small cell lung carcinoma (8 papers, 2017 to 2024). A group of at least three distinct histological types of lung cancer, including non-small cell squamous cell carcinoma, adenocarcinoma, and large cell carcinoma. "The association of HOXA-AS2, HOXA11,HOTTIP, HOXA1, HOXA3 and HOXA4 expression with survival of non-small-cell lung cancer." (PMID 39121297, 2024). "For instance, lncRNA HOTTIP was upregulated in lung squamous cell carcinoma and was considered an independent prognostic marker in early-stage non-small cell lung cancer." (PMID 35635595, 2022). "This lncRNA-miRNA-mRNA network is similar to another study which has suggested that HOTTIP up-regulates the expression of high mobility group B3 by binding to miR-615-3p in non-small cell lung cancer cells." (PMID 33585440, 2020). "Previous data revealed that the expression of HOTTIP and PD-L1 was simultaneously dysregulated in non-small cell lung cancer." (PMID 31533774, 2019). "Additionally, Shi and his colleagues confirmed that HOTTIP is negatively correlated to miR-615-3p in non-small cell lung cancer cells." (PMID 34069089, 2021). "The combined aberrant expression of HOXA13/HOTTIP related to the promotion of cell proliferation and in vivo/in vitro metastases, has been also reported in ESCC cells and in non-small-cell-lung cancer (NSCLC)." (PMID 31137568, 2019). "However, the prognostic impact of HOTTIP has not yet been explored in non-small-cell lung cancer (NSCLC)." (PMID 30819158, 2019).